IL1B (interleukin 1 beta)
Diseases named in the same sentence as IL1B in open-access papers (continued):
Sharing a sentence is not in itself a finding about the gene and the disease.
abscess (36 papers, 2009 to 2025). An inflammatory process characterized by the accumulation of pus within a newly formed tissue cavity which is the result of a bacterial, fungal, or parasitic infection or the presence of a foreign body. "In staphylococcal skin infection, neutrophils are a primary source of IL-1β, and IL-1β deficiency impairs bacterial clearing and abscess formation." (PMID 41037009, 2025). "In contrast, infected skin samples from IL-1β−/− PMN→IL-1β−/− mice and IL-1β-deficient mice had markedly decreased neutrophil recruitment with minimal abscess formation and decreased myeloperoxidase (MPO) activity (which correlates with the degree of neutrophil infiltration)." (PMID 23209417, 2012). "Neutrophil-derived IL-1β, in the absence of other cellular sources of IL-1β, was critical for host defense since adoptive transfer of IL-1β-expressing neutrophils was sufficient to restore the impaired neutrophil recruitment and abscess formation in S. aureus-infected IL-1β-deficient mice." (PMID 23209417, 2012). "Furthermore, neutrophil-derived IL-1β was essential for host defense since adoptive transfer of IL-1β-expressing neutrophils was sufficient to restore the impaired neutrophil abscess formation in S. aureus-infected IL-1β-deficient mice." (PMID 23209417, 2012). "This interpretation aligns with the known role of TNF-α and IL-1β in abscess wall formation and containment of infection." (PMID 41531628, 2025). "While IHC analysis for IL1β protein revealed marked positive brown immunoexpression in LNs, liver, and MG abscess, moderate positive brown expression was observed in pulmonary pyogranuloma." (PMID 36670836, 2023). "Interleukin (IL)-1β is a potent cytokine promoting neutrophil migration and triggering abscess formation in response to S. aureus skin infection." (PMID 36123529, 2022). "Upregulation of IL-1β exacerbates the inflammation contributing to the recruitment of other immune cells to the lesion, and to the pus formation seen in HS abscess." (PMID 36291580, 2022). "Neutrophil-derived IL-1β also plays a critical role in optimal neutrophil recruitment to the site of infection, proper abscess formation, and improved infection outcome." (PMID 33690673, 2021). "A similar study demonstrated that during the intradermal infection, the inducible IL-1β response of the bone-marrow-derived recruited cells of the abscess was a more critical determinant for host defense." (PMID 32010088, 2019). "Mice co-injected with NaP had a significantly lower production of IL-1β, a signature cytokine of S. aureus abscess formation, compared with those injected with NaA or NaB." (PMID 31275281, 2019). "Here we analysed inflammatory scores, parakeratosis and presence of micro-abscesses in the context of IL-1β mRNA expression." (PMID 30002960, 2018). "An effective host response against S. aureus skin and soft tissue infection (SSTI) is dependent on IL-1β induced IL-17 expression by resident skin γδ T cells leading to neutrophil recruitment, abscess formation and eventual bacterial clearance." (PMID 24098366, 2013). "An optimal host response against Staphylococcus aureus skin and soft tissue infections (SSTI) is dependent on IL-1β and IL-17 mediated abscess formation." (PMID 24098366, 2013). "Rather, a feed-forward mechanism that involves early recruited neutrophils serving as a source of IL-1β is essential for amplifying and sustaining the neutrophilic response to promote optimal abscess formation and bacterial clearance." (PMID 23209417, 2012). "At 4 hrs, the earliest IL-1β-expressing cells were found almost exclusively within the dermis at the site of abscess formation." (PMID 23209417, 2012). "The neutrophil-derived IL-1β is sufficient to amplify and sustain their recruitment that promotes neutrophilia and effective neutrophil abscess formation." (PMID 23209417, 2012).
abscess (continued). "Although a link between neutrophil recruitment and IL-1β during S. aureus infections was previously documented, our work defines the primary mechanism by which effective neutrophil abscess formation occurs." (PMID 23209417, 2012). "In summary, we have identified that neutrophil-derived IL-1β is essential for amplifying the neutrophilic response to promote abscess formation and clearance of a S. aureus skin infection." (PMID 23209417, 2012). "Here, we found that adoptively transferred wt neutrophils could rescue the immune impairments in IL-1β-deficient mice, indicating neutrophils are the predominant hematopoietic cellular source of IL-1β that was sufficient for effective neutrophil recruitment and abscess formation." (PMID 23209417, 2012). "Furthermore, post-drainage, there is a sharp decline in pyrogens within the abscess cavity, such as endotoxins, IL-1β, and TNF-α." (PMID 41585276, 2025). "By inhibiting GSDMD, it may be possible to reduce the release of IL-1β and IL-18, thereby dampening the inflammatory response and preventing the progression of lesions into chronic, scarring abscesses and tunnels." (PMID 41007405, 2025). "Deletion of the gene encoding the nuclease toxin EsaD, or its chaperone, EsaE, from strain USA300 resulted in reduced IL-1β secretion in a murine bloodstream infection model, while deletion of esaD in strain Newman led to fewer abscesses and a reduced bacterial load in a similar model." (PMID 41384497, 2025). "Production of the innate cytokine IL-1β was also assessed, as this cytokine has been shown to be important in the recruitment of neutrophils to the site of infection during S. aureus skin infection and for abscess formation." (PMID 38973612, 2024). "Increasing the clearance rate of CA-MRSA could also decrease initial local concentrations of IL-β, given that CA-MRSA stimulates the secretion of IL-1β by neutrophils and that neutrophils are the primary source of IL-1β in subcutaneous abscesses." (PMID 39771599, 2024). "However, there were several interactions between dietary Zn treatment and abscess presence for IL-6 and IL-1β production." (PMID 38764468, 2024). "IL-1β-derived neutrophils are essential for abscess formation and clearance of S. aureus infection." (PMID 38112465, 2024). "Interestingly, we have shown that IL-1β/MyD88 actions in neutrophils are necessary for S. aureus abscess formation." (PMID 30102746, 2018). "Indeed, IL-1β produced by neutrophils has been shown to be crucial for abscess formation in a mouse model of S. aureus cutaneous infection." (PMID 26135738, 2015). "Of the host genes tested, we found that transcripts encoding IL-8, IL1β, oncostatin M-like, CCR1, CXCR1 (IL8RA), CCL4 (MIP-1β) and CCL3 (MIP1α)-like proteins were among the most highly up-regulated transcripts during S. aureus abscess formation." (PMID 25719526, 2015). "Consistent with protection, SQ treatment with CPDI-02 increased local levels of IL-1β, IL-6, and CXCL1 and NP recruitment to the abscess." (PMID 39771599, 2024). "After S. aureus skin infections, the production of proinflammatory cytokines and other inflammatory mediators (such as IL-1β and TNF) would promote neutrophil recruitment from the bloodstream to form an abscess to facilitate bacterial clearance." (PMID 37127622, 2023). "The α toxin produces IL-1β via TLR2, NOD2, FPR1, and ASC/NLRP3 inflammasome induced by neutrophils, and IL-1β can induce thymic stromal lymphopoietin and contribute to abscess formation." (PMID 35878202, 2022). "In the subcutaneous lesions caused by USA300 wild type or Δpvl/ΔlukGH strains, the levels of IL1B and IL8 were increased in numerous macrophages and neutrophils at and within the margins of abscesses." (PMID 25719526, 2015). "It is likely that AT neutralization by 2A3 results in increased IL-17 and IL-1β production, leading to increased levels of MIP-2α MCP-1α and G-CSF thereby resulting in neutrophil abscess formation and bacterial clearance." (PMID 24098366, 2013).
abscess (continued). "At day 4 post-infection, abscess tissue of infected mice treated with NO-np contained significantly higher quantities of TNF-α, IFN-γ, IL-12, IL-1β, MCP-1, and TGF-β than that of np or untreated mice." (PMID 19915659, 2009). "On day 56, there was a tendency for increased IL-1β after stimulation with LPS in abscessed steers compared to non-abscessed steers (abscess P = 0.09)." (PMID 38764468, 2024). "For IL-1β, Zn150 non-abscess was increased compared to Zn100 non-abscess and Zn100 abscess, all other treatments were not different." (PMID 38764468, 2024). "GO analysis with the unique differential promoters involved in Munro’s abscess formation revealed neutrophil and leukocyte chemotaxis as the highest enriched biological processes which include genes like HRH1, PDE4D, CCL25, AIF1, ADAM10, FFAR2, IL1B and TREM1." (PMID 30092825, 2018). "Further, neutrophil-derived IL-1β, in the absence of other cellular sources of IL-1β, was sufficient for neutrophil recruitment, abscess formation, and bacterial clearance." (PMID 23209417, 2012). "Our data show that iKIR enhances specifically the production of pro-inflammatory cytokines known to drive proper abscess formation and improved infection outcome (IL-1β), neutrophil recruitment (CXCL1 and CXCL2), but not monocyte recruitment (CCL2) in response to MRSA skin infection." (PMID 33690673, 2021). "Previously, we demonstrated that auranofin applied topically is effective in significantly reducing the burden of MRSA in an uncomplicated abscess model in mice and in decreasing expression of pro-inflammatory cytokines (TNF-α, MCP-1, IL-1β, and IL-6) that may impair wound healing." (PMID 32350417, 2020). "In fact, previous studies showed that neutrophils but not monocytes/macrophages were the predominant source of IL-1β at a site of Staphylococcus aureus cutaneous infection and demonstrated that neutrophil-derived IL-1β was critical for abscess formation and host defense." (PMID 29515581, 2018). "However, immunohistochemistry with an anti-IL-1β mAb identified scattered IL-1β-expressing cells within the abscess at 24 hrs in wt PMN→IL-1β−/− mice but not in IL-1β−/− PMN→IL-1β−/− mice." (PMID 23209417, 2012). "On day 13, after stimulation with PAM3CSK, Zn150 steers without abscesses had the greatest cytokine (IL-6 and IL-1β) production, and were higher than CON abscessed steers and Zn100 steers without abscesses." (PMID 38764468, 2024). "There was a tendency for increased IL-1β after PAM3CSK stimulation on day 56 where Zn100 abscess, Zn150 non-abscess, and abscess were increased compared to Zn100 non-abscess (TRT × abscess P = 0.06)." (PMID 38764468, 2024).
retinal degeneration (36 papers, 2013 to 2025). Degeneration of the retina. "Although IL-1β/IL-1R1 signaling has been implicated in cytotoxic processes during retinal degeneration, accumulating evidence points to its pro-survival role under certain conditions." (PMID 40002456, 2025). "IL-1β dysfunction has been associated with excessive inflammation in retinal degenerations using animal models, including those modeling key features of dry AMD." (PMID 31379825, 2019). "Several cytokines and chemokines including MIP-1α (CCL3), MIP-1β (CCL4), MCP-1 (CCL2), MCP-3 (CCL7), TNF-α, IL-1β and IL-6 have been implicated in photoreceptor-microglial crosstalk and retinal degeneration." (PMID 27814376, 2016). "Interestingly, using animal models, an association of IL-1β dysfunction with excessive inflammation in retinal degenerations has been found." (PMID 36012296, 2022). "Matrix metalloproteinases (MMPs), responsible for the protein degradation of the extracellular matrix (ECM), have also been linked to IL-1β in retinal degenerations, with wet AMD patients carrying SNPs in MMP-1 and MMP-7 genes found to have a higher serum concentration of IL-1β." (PMID 31379825, 2019). "In P23H model of retinal degeneration, an increased expression of Tnf-α, Il-1α, and Il-1β could, at least in part, explain the increased loss of photoreceptors observed in LPS-injected P23H rats." (PMID 29500424, 2018). "Previous studies using injections of recombinant IL-1ra, an endogenous antagonist for IL-1r1, have suggested a role for IL-1β in propagating retinal degeneration, using models of photo-oxidative damage in Cx3cr1-deficient mice, laser-induced CNV, and retinitis pigmentosa." (PMID 28438165, 2017). "Therapies targeting IL-1β (e.g., canakinumab, an IL-1β inhibitor) are under investigation for their neuroprotective potential in retinal degeneration." (PMID 40722794, 2025). "Key inflammatory mediators such as tumor necrosis factor-alpha (TNF-α), interleukins (IL-6, IL-1β), and activated microglia contribute to retinal degeneration." (PMID 40428167, 2025). "Activated microglia itself secretes several inflammatory cytokines (e.g., TNFα, IL-1β and IL-6) and leads to the production of ROS (as discussed in the previous chapter), increasing photoreceptor damage and ultimately leading to retinal degeneration." (PMID 38370034, 2024). "There is a strong correlation between DIM-conserved markers in the brain and the proinflammatory molecules known to be cytotoxic in retinal degeneration, including Il-1α, Il-1β, Tnf-α, and Tlr4, as well as NO and ROS production." (PMID 36779012, 2023). "NLRP3 was detected in cone PRs and one-third of reactive microglia in P23H rhodopsin mutant retinas, which also upregulates the expression of mature IL-1β and IL-18, as well as cleaved caspase-1, indicating inflammasome activation during retinal degeneration." (PMID 36389729, 2022). "Upregulation of Tlr2, Il1b, Myd88 and Tirap was found in RP model rd10 and P23H mice, demonstrating TLR activation involvement in RP-associated retinal degeneration." (PMID 36389729, 2022). "These increases, as well as the increase in Il1β expression, were consistent but of a lesser magnitude than those observed in rd10 retinas, likely reflecting the slower pace of retinal degeneration of the P23H/+ model." (PMID 34360582, 2021). "Little has been reported on ASC in the literature, specifically in relation to retinal degenerations, however, what is clear is that from gene expression studies, Asc gene up-regulation can be mirrored to that of Casp-1 and Il-1β, along with cell death." (PMID 32041990, 2020). "These hallmark pathogenic features are evident in both acquired and inherited forms of retinal degenerations, and are strongly correlated to the activation of the two most characterized IL-1 family members, IL-1β, and IL-18." (PMID 31379825, 2019).
retinal degeneration (continued). "The authors found that IL-33 was released by Müller cells after light exposure, which then induced CCL2, IL-6 and IL-1β expression through autocrine activation of Müller cells and promoted immune cell infiltration and retinal degeneration." (PMID 31796062, 2019). "We will further detail the localization and pro-inflammatory functions of IL-1β in retinal degenerations later in this review, focusing on its role in dry AMD pathogenesis." (PMID 31379825, 2019). "We found less microgliosis and lower expression of CD68 and IL-1β, which is in line with the published effects of minocycline in an ischemia-reperfusion model of retinal degeneration." (PMID 30042155, 2018). "We have previously shown that in photo-oxidative damage, inflammasome expression and IL-1β production were observed in retinal degeneration, where IL-1β was found to be expressed by microglia and macrophages at the site of photoreceptor degeneration." (PMID 30126455, 2018). "The data from this study supports the use of IL-1β inhibition strategies as a therapeutic approach to reduce chemokine synthesis, and subsequent macrophage accumulation and photoreceptor death in retinal degenerations." (PMID 28438165, 2017). "We thenassessed if the Tn-induced inflammatory marker IL-1β was capableof inducing retinal degeneration by injecting C57BL6 mice with a recombinantIL-1β." (PMID 25522272, 2014). "Developing effective therapeutics to target GSDMD could, therefore, be useful in slowing the progression of retinal degenerations by preventing the release of pro-inflammatory mediators, including IL-1β and dampen overall immune response." (PMID 37864169, 2023). "Overall, we demonstrate increased retinal expression of GSDMD in degeneration, and show that inhibition of GSDMD function in-vivo animal models of retinal degeneration and in-vitro reduces release of pro-inflammatory cytokine IL-1β, providing overall protection." (PMID 37864169, 2023). "This provides a new mechanism for GSDMD-mediated retinal degeneration, where IL-1β may be packaged and sent to distant cells via EV to propagate inflammation." (PMID 37864169, 2023). "Moreover, in the in vivo, ex vivo, and in vitro models of retinopathy of prematurity, IL-1β was notably increased in the RPE/ choroid and caused choroidal involution, loss of RPE and photoreceptors, retinal degeneration, and visual deterioration." (PMID 35576057, 2022). "Moreover, the identity (and presumed location) of cells generating IL-1β and harboring IL-1RI remains to be clarified in order to better elucidate the role that IL-1β plays in retinal degeneration." (PMID 33246504, 2020). "Conversely, in pathological conditions, MPs are activated, invade the outer and subretinal space, and secrete pro-inflammatory cytokines, including tumor necrosis factor-α, interleukin (IL)-6, and, importantly, IL-1β, which is considered to play a major role in retinal degeneration." (PMID 33246504, 2020). "Targeting IL-1β as a therapeutic approach to reduce chemokine synthesis in the damaged retina may be beneficial in slowing the progression of retinal degenerations." (PMID 28438165, 2017). "Our work demonstrates that in the context ofan established animal model for ocular disease, the persistent activation of theUPR could be responsible for promoting retinal degeneration via the UPR-inducedpro-inflammatory cytokine IL-1β." (PMID 25522272, 2014). "In addition, resident microglia can proliferate and produce high levels of TNFα and IL-1β, which subsequently lead to the acceleration of retinal degeneration." (PMID 23828046, 2013). "Our finding suggests that the increased number of AF spots is related to resident microglia proliferation, which established a cytokine milieu that was skewed to inflammation by upregulating the expression of the IL-1β, IL-6 and TNFα genes, which subsequently accelerated retinal degeneration." (PMID 23828046, 2013).